BDNF (brain derived neurotrophic factor)
Diseases named in the same sentence as BDNF in open-access papers (continued):
Sharing a sentence is not in itself a finding about the gene and the disease.
brain injury (97 papers, 2011 to 2026). Acute and chronic (see also brain INJURIES, CHRONIC) injuries to the brain, including the cerebral hemispheres, CEREBELLUM, and brain STEM. "Studies have pointed out that traumatic brain injury (TBI) can activate the BDNF/TrkB pathway to cause changes in expression of BDNF mRNA." (PMID 35414007, 2022). "Olfactory function was proposed as a potential indicator of structural and functional injury after concussion, as well as a structure of the brain known to be able to regenerate and susceptible to BDNF." (PMID 33808272, 2021). "BDNF concentration was significantly higher in children with severe concussion and loss of consciousness (3826.00 pg/mL) than in the control group." (PMID 32987792, 2020). "In traumatic brain injury, neurological function improvement was associated with the upregulated BDNF expression, while the blockade of BDNF exacerbated neurological function deficits." (PMID 30766469, 2018). "This study attempted to elucidate the role of the BDNF variant rs6265 in emotional symptoms following mild traumatic brain injury (mTBI)." (PMID 29357818, 2018). "Decreased levels of serum BDNF have been associated with higher clinical severity of traumatic brain injury and with decreased 6-month functional outcome scores." (PMID 27468268, 2016). "Serum levels of Brain-Derived Neurotrophic Factor (BDNF) within the first week after brain injury were associated with functional memory scores at 6 and 12 months after injury; lower serum BDNF levels in the early post-injury period were associated with poor memory scores." (PMID 36970504, 2023). "The most studied polymorphism of BDNF in humans is rs6265 (Val66Met), in relation to normal cognitive function, effects on psychiatric, neurodegenerative and neuroinflammatory disease, and traumatic brain injury." (PMID 33808272, 2021). "There is controversy from human studies as to whether the BDNF Val66Val or Val66Met allele is the risk factor for worse outcomes after brain trauma." (PMID 31787925, 2019). "Recently it was shown that the GH stimulatory effects on cognitive function in rats with traumatic brain injury is associated with increments of hippocampal and prefrontal Brain Derived Neurotrophic Factor (BDNF) mRNA expression and its receptor TrkB mRNA expression." (PMID 26041981, 2015). "Of the statement above, the author’s interest arose to research the effect of Nigella sativa seed extract and propofol on BDNF as neuroplasticity and neuroprotection of traumatic brain injury in rats (Rattus novergicus)." (PMID 39810851, 2024). "This review also identifies that muscle strength and endurance training improved the level of serum BDNF in brain injury patients." (PMID 39355076, 2024). "For example, ERK1/2 activated by brain-derived neurotrophic factor (BDNF) was shown to inhibit apoptosis by reducing caspase-3 activity in hypoxic–ischemic brain injury." (PMID 39771472, 2024). "BDNF administration can have neuroprotective effects and is associated with improvements in functional and behavioral outcomes, suggesting the importance of BDNF in recovery from ischemic brain injury in addition to TBI." (PMID 38397427, 2024). "In a recent study, it was reported that DEX showed beneficial effects by activating the BDNF signalling pathway in male rats with kainic acid-induced brain injury." (PMID 39768379, 2024). "Our previous animal study found that MNS exerted wake-promoting effects in comatose rats after traumatic brain injury by upregulating orexin-A and BDNF." (PMID 37168716, 2023). "Using H4K5ac ChIP-PCR, we indeed found a significant upregulation in the levels of H4K5ac at the BDNF 5’ end with romidepsin treatment, as previously reported in a traumatic brain injury model." (PMID 37598220, 2023). "According to numerous studies, the number of neurons in the hippocampus and BDNF concentrations in the cranial cortex were both found to increase following ischemic brain injury." (PMID 37371971, 2023).
brain injury (continued). "For its characteristics on neurons and synapses, BDNF has been discovered to play a momentous role in neuronal survival and synaptogenesis that occur in reparative processes after traumatic brain injury." (PMID 37114226, 2023). "Synaptogenesis and restoration of damaged synapses in chronic neurodegenerative disease or acute or chronic traumatic brain injury occur after PBM stimulation through regulation of brain-derived neurotrophic factor (BDNF)." (PMID 36034819, 2022). "This is consistent with results where GH administration stimulated the synthesis of BDNF in animals with traumatic brain injury and improved cognitive functions." (PMID 34567109, 2021). "BDNF increases the expression of the antiapoptotic Bcl-2 protein, and thereby exerting part of its neuroprotective effects against brain injuries." (PMID 33936582, 2021). "Brain-derived neurotrophic factor (BDNF) has been recognized as a protective effector of synaptic transmission and cognitive function after HI brain injury." (PMID 32470970, 2020). "In a recent study, miR-155 targeted BDNF, and downregulation of miR-155-targeted BDNF transcripts protected against ischaemic brain injury." (PMID 33029119, 2020). "In this study we used dBcAMP to promote the secretion of BDNF and enhance neuronal survival in brain injuries." (PMID 30135639, 2018). "Neural plasticity after brain injury is activity dependent and the level of brain-derived neurotrophic factor increases depending on rehabilitation intensity." (PMID 29095902, 2017). "After traumatic brain injury serum BDNF is acutely decreased correlating with injury severity, and therapies that increase brain BDNF expression, such as environmental enrichment, show promise for cognitive recovery." (PMID 27468268, 2016). "In 113 traumatic brain injury patients with serum BDNF levels measured 0–6 days (acute) and 6–12 months (chronic) post-injury, serum BDNF levels were reduced after traumatic brain injury at all time points." (PMID 27468268, 2016). "BDNF, a member of the neurotrophin family, exerts a protective effect against ischemic brain injury via antiexcitatory amino acids, the inhibition of inflammatory reactions, and decreased apoptosis." (PMID 26523278, 2015). "Our previous study has shown that CG matrix implantation increased tissue concentration of BDNF following surgical brain trauma." (PMID 25309917, 2014). "On the other hand, inclusion of 1.2% DHA in the diet was able to increase BDNF protein levels in rat hippocampal tissue after brain trauma." (PMID 23351783, 2013). "Animals that exercise after brain injury show an increase in the expression of neurotrophic factors, such as BDNF, HGF, and FGF-2, which regulate neuronal survival and differentiation, synaptic plasticity, as well as angiogenesis in the brain." (PMID 24098645, 2013). "For example, curcumin supplementation has been shown to reduce cognitive and locomotor deficits via normalizing levels of BDNF in rodents with brain trauma." (PMID 22911773, 2012). "DHA has been shown to normalize levels of brain-derived neurotrophic factor (BDNF), reduce oxidative damage, and counteract learning disabilities in animal models of brain trauma." (PMID 22911773, 2012). "Synaptic plasticity and neurotrophic factors (expression of synaptophysin, BDNF, TrkB) are involved in neurorepair activity, leading to functional recovery following acute brain injury." (PMID 21733162, 2011). "The Brain‐derived neurotrophic factor gene (BDNF) plays a critical role in neuroplasticity and dopamine pathways, making it a key focus in studies exploring genetic influences on cognitive recovery after brain injuries." (PMID 41476008, 2026). "Furthermore, BDNF has been proven to promote neural repair and regeneration after brain injury, and its expression is upregulated in various types of brain injuries." (PMID 40589985, 2025).
brain injury (continued). "Similar to BDNF, IGF-1 also plays an important role after brain injury and studies have shown that IGF-1 may mediate the exercise-induced regulation of BDNF and cognitive improvements after brain injury." (PMID 38397427, 2024). "Other growth factors may also play a role in rehabilitation and recovery after brain injury, often interacting closely with BDNF." (PMID 38397427, 2024). "Furthermore, some studies have shown that pre-conditioning, or exercising prior to brain injury, can improve BDNF concentrations post injury and improve recovery after ABI, as well." (PMID 38397427, 2024). "This evidence suggests that brain injury could elevate BDNF expression for self-rehabilitation by mimicking the endogenous protective response of the brain." (PMID 37114226, 2023). "In addition to growth factors such as brain-derived neurotrophic factor (BDNF) up-regulating neurogenesis, S100B contributes to hippocampal network repair after brain injury as well as memory consolidation during development." (PMID 36076994, 2022). "This study indicates that dBcAMP protects neurons from degeneration by enhancing the production of BDNF and may be considered for use as therapeutic agent for treatment of brain injuries." (PMID 30135639, 2018). "Previous studies have indicated that the positive-feedback loop between CREB and BDNF could become active in several neuronal populations in response to ischemic brain injury." (PMID 28408940, 2017). "Acute serum BDNF may be a viable predictive biomarker for mood and cognitive complications within the 1st year after traumatic brain injury, and BDNF may provide a treatment window in the acute phase that affects long term recovery." (PMID 27468268, 2016). "For example, plasma BDNF was found to be an independent predictor of 4-year major coronary events in patients with angina pectoris and low serum BDNF levels have recently been reported to be predictive of vascular brain injury." (PMID 26469350, 2015). "This BDNF’s neuroprotective action was blocked by pretreatment with an ERK1/2 inhibitor, U0126, but not with an PI3-K inhibitor, wortmannin, suggesting a central role of the ERK1/2 pathway in mediating the neuroprotecive effect of BDNF on H-I brain injury in developing brain." (PMID 24551199, 2014). "In addition, LM22A-4 was reported to match BDNF efficacy in prevention of neuronal death and improve motor learning after traumatic brain injury." (PMID 24503862, 2014). "In addition, research with rodent models has shown that exercise in the subacute time period following brain injury (> 1 week) increases angiogenesis and concentrations of neurotrophins such as Brain-derived neurotrophic factor (BDNF), which are thought to act as mediators of recovery." (PMID 35473570, 2022). "Furthermore, recent and past studies have reported that brain-derived neurotrophic factor (BDNF) has a critical role in ischemic brain injury and that it could also be a potential biomarker for ischemic and traumatic brain injuries." (PMID 35456999, 2022). "BDNF plays central roles in synaptic plasticity and neuronal development, and animal models suggest that exogenous BDNF has neuroprotective effects, improving neurological deficits in different brain injuries, including TBI, hypoxic-ischemic brain injury, and subarachnoid hemorrhage." (PMID 32565776, 2020). "Neurotransmission-related genes (BDNF, COMT, DRD1–3, DBH, SLC6A4, HTR2A, APOE) influenced motivation, fatigue, cognitive performance, and brain injury recovery." (PMID 41596414, 2026). "Brain-derived Neurotrophic Factor (BDNF), a nerve growth factor, plays a crucial role in neuronal survival, adaptation, and response to ischemic brain injury, with implications for endothelial cells (ECs) survival and neo-angiogenesis in ischemic tissues." (PMID 39749215, 2024).
brain injury (continued). "In a model of traumatic brain injury, HBOT promoted the expression of neurotrophic factors such as NGF, brain-derived neurotrophic factor (BDNF), glial cell line-derived neurotrophic factor (GDNF), and neurotrophin-3 (NT-3) in vivo." (PMID 38396709, 2024). "Evidence from non-human studies suggests that docosahexaenoic acid (DHA) enhances the expression of brain-derived neurotrophic factor (BDNF) and provides a positive influence against tissue damage induced by brain injury." (PMID 39519537, 2024). "GH treatment has been shown to increase expression of brain-derived neurotrophic factor (BDNF) and improve cognitive outcomes in traumatic brain injury." (PMID 35465399, 2022). "It is well known that some important neural factors, such as vascular endothelial growth factor (VEGF) and brain-derived neurotrophic factor (BDNF), have a protective effect against ischemic brain injury and are potential therapeutic targets." (PMID 35937889, 2022). "In animal models of traumatic brain injury (TBI), BDNF expression is upregulated in the hippocampus and cerebral cortex; peripheral levels of BDNF after acute brain injury in humans have been scarcely evaluated." (PMID 32565776, 2020). "Recently, brain-derived neurotrophic factor (BDNF) is also known to be useful to neuronal functions and protect the CNS against a variety of brain injuries." (PMID 29881418, 2018). "Currently, there is a significant amount of experimental data suggesting that brain-derived neurotrophic factor (BDNF) is an effective neuroprotective agent for various central nervous system (CNS) diseases and brain injuries." (PMID 30081596, 2018). "We decided to analyse the effect of brain trauma and galectin-3 gene deletion on the mRNA levels of NGF and BDNF." (PMID 28128358, 2017). "In another study, induction of striatal neurogenesis by the intraventricular administration of brain-derived neurotrophic factor (BDNF) and EGF promoted functional recovery in a mouse model of neonatal hypoxic-ischemic brain injury." (PMID 28173860, 2017). "The enhancement of hippocampal brain-derived neurotrophic factor (BDNF) content and increased cognitive process in rodent models of brain trauma are observed during DHA dietary supplementation." (PMID 26966612, 2016). "In particular, brain derived neurotrophic factor (BDNF) is highly responsive to activity, increasing in response to wheel running, environmental enrichment, and task-specific practice following brain injury." (PMID 25883586, 2015). "Brain-Derived Neurotrophic Factor (BDNF) is a key neurotrophic factor known for enhancing synaptic plasticity, promoting neuronal survival, and facilitating functional recovery in various brain injuries." (PMID 41304786, 2025). "We and others identified that target-derived BDNF is involved in the reorganization of CST axons and corticorubral axons following neonatal brain injury." (PMID 40191711, 2025). "It aims to explore the effect of target task-oriented phase training on fibrinogen (Fbg), angiopoietin (Ang-1), vascular endothelial growth factor (VEGF), serum brain-derived neurotrophic factor (BDNF), and quality of life in post-operative patients with brain trauma." (PMID 39139152, 2024). "In this context, although our current study focused on changes in the structural components of the NVU, it would be of interest to examine changes in BDNF and other growth factors with reference to changes in the NVU after HI-injury-related brain injury in the neonatal in future studies." (PMID 35456999, 2022). "Moreover, it should be noted that the activation of the BDNF pathway, which was also observed to be activated in our IPA analysis upon DHA treatment, had been previously observed to be modulated by DHA after brain trauma." (PMID 36678710, 2022).
brain injury (continued). "Quercetin also increased the activity of GPx, SOD, and CAT in traumatic brain injury, decreased the elevated MMP-9 level, and also activated the brain-derived neurotrophic factor (BDNF), tropomyosin receptor kinase B (TrkB), and PI3K/Akt signaling pathway in cerebral focal ischemia." (PMID 35035667, 2022). "In addition, microglia-derived neurotropic factors, such as brain-derived neurotrophic factor (BDNF), promote learning-dependent synaptic formation and protect neurons from brain injuries." (PMID 34795562, 2021). "Additionally, trophic signalling plays an important role in neuroprotection, with the role of BDNF and FGF signalling in recovery following hypoxic ischaemic brain injury extensively studied (reviewed in refs.43,44)." (PMID 29681622, 2018). "We found that the level of BDNF was elevated spontaneously after TBI and reached up to the peak at 12 h, suggesting that the expression of BDNF enhanced under condition of acute brain injury by self-compensatory regulation, thereby promoting the repair of damaged tissue." (PMID 28243312, 2017). "We recently described differences in the concentration of SCFAs in the stool of extremely premature infants with or without brain injuries, which led us to look closer at the effect of sodium‐butyrate, sodium‐acetate and sodium‐propionate on the secretion of BDNF by PBMCs." (PMID 40170375, 2025). "The lack of statistical differences for BDNF and IL-8 between children with mild or severe concussion could indicate that their elevated levels may not result from significant structural brain damage but rather reflect a functional disturbance." (PMID 32987792, 2020).